CDKN1A (cyclin dependent kinase inhibitor 1A)
Diseases named in the same sentence as CDKN1A in open-access papers (continued):
Sharing a sentence is not in itself a finding about the gene and the disease.
leiomyoma (1 paper, 2021). A well-circumscribed benign smooth muscle neoplasm characterized by the presence of spindle cells with cigar-shaped nuclei, interlacing fascicles, and a whorled pattern. "Most of the leiomyoma DEGs were found upregulated in F compared to the MF or M; however, some genes, including CDKN1A, L1CAM, SLC7A5, CCND1, IGF1R, and PTHLH, were only increased in MF vs. M and F vs. M comparisons." (PMID 33807176, 2021).
lupus nephritis (1 paper, 2021). Glomerulonephritis in the context of systemic lupus erythematosus. "In this study, we evaluate the variants on three genes STAT4, CDKN1A, and IRF5 and their association with lupus nephritis." (PMID 33687153, 2021). "Thus, in this report, we evaluate the polymorphisms of these three genes (STAT4, CDKN1A and IRF5) and their association with the phenotype of patients with Lupus nephritis." (PMID 33687153, 2021).
metastatic prostate carcinoma (1 paper, 2013). A carcinoma that arises from the prostate gland and has spread to other anatomic sites. "In addtion, the identified interactions in metastatic prostate cancer contain several experimentally confirmed targets of hsa-miR-143 and −145, including CLINT1, CDKN1A, IRS1, MAPK7, PPM1D and SOD2." (PMID 23782521, 2013).
morbid obesity (1 paper, 2021). An excess of body weight, normally defined as an individual with a body mass index greater than 35 or a body weight greater than one hundred percent of ideal body weight. "The difference in expression of Btg2 and Cdkn1a in the mice fed the WD and AD suggest morbid obesity and nutritional inadequacies influence the pathophysiology of kidney injury via different cellular mechanisms and may have different long-term outcomes." (PMID 33946347, 2021).
myopia (1 paper, 2025).
necrotizing enterocolitis (1 paper, 2022). Necrotizing enterocolitis (NEC) is a devastating disease that affects mostly the intestine of premature infants. "Moreover, Cdkn1a was upregulated in ferroptosis--related necrotizing enterocolitis However, the role of Cdkn1a in SCM has not been investigated." (PMID 35495160, 2022).
nephritis (1 paper, 2008). Inflammation of renal tissue. "Increased levels of transcripts for pathway members including JAK3, STAT3, SOCS3, PTPN1, CDKN1A, RRAS and MAPK1 were observed in nephritis." (PMID 18980674, 2008).
neutropenia (1 paper, 2023). A decrease in the number of neutrophils found in the blood.
Pancreatic NETs (1 paper, 2025). "Pancreatic NETs frequently exhibit changes in genes such as MEN1, DAXX, ATRX, TSC1, TSC2, CDKN1A, and CDKN1B, along with alterations in CDKN2A and SETD2 in metastatic lesions." (PMID 41426335, 2025).
papillary thyroid carcinoma (1 paper, 2022). "For example, lncAB bound KH-type splicing regulatory protein (KHSRP) and also decreased the expression of KHSRP in papillary thyroid carcinoma, thus increasing CDKN1a (p21) expression and decreasing CDK2 expression to repress cell proliferation." (PMID 36267418, 2022).
Psoriasiform dermatitis (1 paper, 2016). A skin abnormality characterized by redness and irritation, with thick, red skin that displays flaky, silver-white patches (scales).
pterygium (1 paper, 2012). A wedge-shaped fibrovascular lesion arising from the bulbar conjunctiva and extending to the cornea.
pulmonary emphysema (1 paper, 2012). A subcategory of chronic obstructive pulmonary disease (COPD). "CDKN1A mediates cigarette smoke-induced inflammation; cigarette smoke increases expression of CAV-1 which is involved in senescence and pulmonary emphysema induction." (PMID 22829758, 2012).
retinopathy of prematurity (1 paper, 2024). A bilateral retinopathy characterized by neovascularization, scarring, retinal detachment, and eventually blindness. "They found that a single 5 μg dose of IVT metformin reduced expression of several key SASP genes, such as Il6, Cdkn1a, and Cdkn2a, as well as decreased protein levels of IRE1α and NF-κB, highlighting the potential therapeutic effects of IVT metformin in retinopathy of prematurity." (PMID 39518910, 2024).
rhabdoid tumor (1 paper, 2009). An aggressive malignant embryonal neoplasm usually occurring during childhood. "Cyclin E can overcome SMARCB1 induced proliferation arrest in RT cell lines also implying involvement of CIP KIP inhibitors in rhabdoid tumor, however in other studies CDKN1A and CDKN1B expression were unchanged by SMARCB1 expression." (PMID 19221586, 2009). "CDKN1C expression was also shown to be generally absent in clinical specimens of rhabdoid tumor, however CDKN1A and CDKN1B expression persisted." (PMID 19221586, 2009). "We identified minor transcriptional upregulation of CDKN1A or CDKN1B in two different RT cell backgrounds following transfection with SMARCB1 however, expression of these genes persisted in clinical specimens of ATRT with inactivated SMARCB1 arguing against a major role in rhabdoid tumor aetiology." (PMID 19221586, 2009).
serous ovarian carcinoma (1 paper, 2015). "We have previously documented the utility of Nutlin-3a in low-grade serous ovarian carcinoma, with up-regulation of cell cycle control, and apoptosis genes including CDKN1A, CDKN2A, PERP, and PUMA." (PMID 26248031, 2015).
small-fiber neuropathy (1 paper, 2021). "After IL-1β-highly responsive clone (6D cells) from noninvasive MCF-7 BC cells were stimulated by IL-1β, the expression of CDKN1A/p21, TP63, small-fiber neuropathy (SFN), and especially BIRC3, was upregulated, which made BC cells resistant to doxorubicin." (PMID 34602858, 2021).
T cell lymphomas (1 paper, 2016). "In T cell lymphomas TCF3 exerts its tumor suppressing function by repression of proto-oncogenes MYC, CDK6 and by up-regulation of cell cycling inhibitor CDKN1A/p21, thereby leading to cell cycle arrest." (PMID 27166193, 2016).
tumor-predisposition syndromes (1 paper, 2025).
Type 1 diabetes (1 paper, 2023). "Interestingly, in humans, senescent beta cells accumulated prior to onset of Type 1 diabetes as seen by the increased expression of CDKN1A (p21), IL-6 and SERPINE-1 in pancreas from autoantibody-positive donors as compared to non-diabetic control donors." (PMID 37822597, 2023). "Interestingly, senescent beta cells accumulated prior to onset of Type 1 diabetes, seen as increased of CDKN1A, IL-6 and SERPINE-1 in autoantibody-positive donors as compared to non-diabetic control donors." (PMID 37822597, 2023).
uterine corpus endometrial carcinoma (1 paper, 2019). A endometrial carcinoma (disease) that involves the body of uterus. "As expected, when analyzing DNA promoter methylation and CDKN1A gene expression, there was a negative correlation between both parameters except for uterine corpus endometrial carcinoma; however, the correlation coefficients were not remarkably high." (PMID 31514410, 2019).
uveitis (1 paper, 2025). An inflammatory process affecting a part of or the entire uvea. "This study identified six significantly upregulated genes (CDKN1A, VCAM1, NFKBIA, ICAM1, IRF1, and CXCL10) and demonstrated that QHRGF exerts therapeutic effects on uveitis using in vivo experiments." (PMID 40718791, 2025). "This study demonstrated that five compounds dock to CDKN1A, indicating the advantages of QHRGF with multiple components and multiple targets in treating uveitis." (PMID 40718791, 2025).
ZIKV infection (1 paper, 2022).
tumor (753 papers, 1995 to 2026). "In the present study, we aimed to clarify the mechanisms underlying CDKN1A-enhanced tumor radioresistance." (PMID 38468925, 2024). "CDKN1A has been shown to be down-regulated in multiple malignant tumors, with its reduced expression or inactivating mutations closely linked to tumor progression." (PMID 39268503, 2024). "Genetic polymorphism frequencies frequently exhibit variations among ethnic groups, suggesting potential ethnic and tumor-specific disparities in the cancer susceptibility associated with CDKN1A c.93C > A polymorphisms." (PMID 37730565, 2023). "p21 is encoded by the CDKN1A gene, which can function as an oncogenic protein or a tumor suppressor, mainly depending on its subcellular localization 7-9." (PMID 35414784, 2022). "In mice, mutations in CDKN2A gene, affecting either or both encoded proteins p16 and p19, or in CDKN1A, result in increased tumour development susceptibility." (PMID 33439271, 2021). "Hypoacetylation of the p21waf1/cip1 (CDKN1A) promoter by HDACs is associated with transcriptional silencing of this tumor-suppressor gene, thus contributing to malignant transformation." (PMID 33339101, 2020). "p21 encoded by CDKN1A is a well-known tumor suppressor that participate in regulating cell proliferation." (PMID 31311512, 2019). "In contrast, the CDKN1ASUPER mouse harboring a third CDKN1A allele has a tumor-suppressive phenotype under genotoxic stress." (PMID 31311187, 2019). "Overexpression of miR-4758 rescued the expression of CDKN1A and the associated increase in proliferation due to miR-519d, suggesting a tumour suppressive role for miR-4758." (PMID 29963264, 2018). "With respect to oncogenesis, the tumor suppressor function of CDKN1A is well established, yet there is also growing evidence for oncogenic properties of CDKN1A-encoded p21." (PMID 25838973, 2015). "We identified CDKN1A that encodes the cyclin dependent kinase inhibitor p21, which activates multiple tumor suppressor pathways." (PMID 26304929, 2015). "For example, p21, encoded by CDKN1A, plays both tumor suppressor activities and paradoxical tumor-promoting activities in cancer." (PMID 26352260, 2015). "We show that LKB1 deficiency impedes physiological UVB-induced CDKN1A degradation, impairing DNA damage repair and consequently contributes to mutagenesis and tumor development." (PMID 25329316, 2014). "The tumour-suppressor gene CDKN1A (encoding p21Waf/Cip1) is thought to be epigenetically repressed in cancer cells." (PMID 23658227, 2013).
tumor (continued). "The critical function of endogenous Myc in this context is to repress expression of cdkn1a, since deletion of c-myc leads to a loss of tumor formation as well as elevated levels of p21Cip1, and co-deletion of cdkn1a fully restores tumor formation." (PMID 22509363, 2012). "Changes in expression of two in vivo identified genes, CCND1 and CDKN1A, encoding important cell cycle regulators were confirmed by IHC and immunoblotting on tumor cells." (PMID 19473496, 2009). "Dasatinib may exert inhibitory effects on ARID1A‐deficient tumour cells by regulating the cell cycle regulatory network associated with cyclin—dependent kinase inhibitor 1A (CDKN1A) and RB1." (PMID 39779467, 2025). "Therefore, this study aimed to explore the mechanisms underlying CDKN1A-enhanced radioresistance in tumor cells." (PMID 38468925, 2024). "CDKN1A encodes the cell cycle inhibitor p21 and serves as a tumor suppressor." (PMID 38203204, 2023). "Finally, we observed that T-ALL onset was accelerated by 37 days in Cdkn1a-deficient mice, compared to the 53 day acceleration found in Heb/Tcf12+/- mice, confirming a tumor-suppressor function for Cdkn1a." (PMID 35401501, 2022). "However, in a tumor environment with mutated ARID1A, the MVIH inhibition is lifted, affecting CDKN1A expression and ultimately leading to tumor progression." (PMID 36359888, 2022). "This sensitization of tumor cells could occur via triggering cell cycle arrest caused by overexpression of p21 (CDKN1A), modulating apoptosis represented by caspase-3/7 activation as well as regulating the expression level of MHC class II." (PMID 33954114, 2021). "Therefore, it is unsurprising that decreased expression or loss of CDKN1A in combination with the loss of a second tumor suppressor gene or activated oncogene has been observed in multiple tumors." (PMID 34065345, 2021). "Interestingly, the higher the expression of CDKN1A, the higher the risk of poor prognosis, but it was significantly downregulated in tumor tissues." (PMID 35096011, 2021). "For example, cyclin-dependent kinase inhibitor 1A (CDKN1A), a tumor suppressor that is downregulated in multiple cancers, is targeted by at least 28 miRNAs and many of which are upregulated together in cancers where CDKN1A has been implicated." (PMID 30123182, 2018). "Our preclinical observation on the existence of a negative correlation between brachyury and p21 expression in tumor cells was then corroborated via analysis of the lung squamous cell carcinoma dataset from (TCGA) for levels of mRNA encoding brachyury (T) and p21 (CDKN1A)." (PMID 29774202, 2018). "We have recently shown that p21Cip1/CDKN1A is involved in the regulation of mitosis and its loss prolongs the mitotic duration accompanied by defects in chromosome segregation and cytokinesis in various tumor cells." (PMID 25483104, 2015).